ENSG00000259932 (novel transcript)
Gene: Long non-coding RNA gene on chromosome 15 (45,198,517 to 45,199,139, reverse strand). Ensembl gene ENSG00000259932.
Gene Ontology:
Molecular function: triplet codon-amino acid adaptor activity
Biological process: translation